VEGFA (vascular endothelial growth factor A)
Diseases named in the same sentence as VEGFA in open-access papers (continued):
Sharing a sentence is not in itself a finding about the gene and the disease.
cancer (continued). "Finally, considering VEGFA is secreted to promote cancer angiogenesis, we also test the VEGFA levels in the culture medium of sh-ALKBH5 U87 cells, and results also indicated knock-down ALKBH5 in U87 cells will lead to less VEGFA expression and secretion." (PMID 38221546, 2024). "Notably, genes with higher expression levels in the bone metastatic tumors demonstrated a pro-angiogenic signature, and were enriched in blood vessel development and VEGFA-VEGFR2 signaling pathways, suggesting the angiogenesis ability of cancer cells in the BMRCC." (PMID 38216635, 2024). "Thus, there may be a positive feedback loop mediated by VEGFA between TNBC cells and macrophages, and this process could be amplified in the development of cancers." (PMID 38169627, 2024). "The phytochemicals NBL, TC, PPR have reported anti-angiogenic activity in several cancer or other disease conditions, however, no study has reported the antiangiogenic property of these phytochemicals against key angiogenic factors VEGFA/VEGFR-2 axis in GBM nor in GBM xenograft CAM model." (PMID 38036978, 2023). "Furthermore, cancer cells produce several growth factors, such as PDGF-B, VEGFA, and TGF-β1, which may trigger the prevalence of a PDGFR+/desmin+ pericyte phenotype and not the PDGFR+/CD13+ phenotype." (PMID 36835266, 2023). "In addition, VEGFA and B, their receptors KDR and FLT1, and downstream TFs, including KLF4 and ETS1, were found in this analysis as targets of cooperative ENHs, in line with the pivotal role of angiogenesis in promoting cancer metastatic spreading." (PMID 37408506, 2023). "Besides VEGFA which was widely known and applied in anti-angiogenic therapy, in our pan-cancer analysis, some genes, like SPP1, STC1 and COL5A2, were not only highly expressed in most tumors, but also risk factors of prognosis." (PMID 36479101, 2022). "The CAFDL signature was significantly positively associated with TGFB1, CD276, CD40, VEGFA, VEGFB, etc., but showed significantly negative correlation with immune checkpoints (such as CD274, PDCD1, CTLA4, TIGHT, and HAVCR2) and anti-cancer immune regulators (IFNG, IDO1, and GZMA)." (PMID 35967425, 2022). "Besides VEGFA, the inhibition of miR-29b could upregulate the expression of other oncoproteins, such as DNMT3b, LOXL2, and MMP2 in some cancers." (PMID 34306080, 2021). "In summary, among the prognostic genes we screened, the potential relationship amongBIRC5, HMOX1, and VEGFA in HCC prognosis had been reported previously, while VPS35might be a newly identified oncogene of HCC, and further, VPS26A and PRKCD were alsofound to have roles related to cancer." (PMID 33351066, 2021). "VEGFA had the worst binding activity to beta-carotene and cannot bind well with quercetin, arachidonic acid, and aloe-emodin, which suggested that VEGFA may not be the direct target of aloe vera in cancer treatment." (PMID 34899953, 2021). "The results showed that there were 9 active components acting on key targets such as VEGFA, VWF, IL6, TNF, NFKB1, respectively, as well as regulating signaling pathways such as AGE-RAGE, FA, Toll-like receptor, PI3K/Akt, NF-κB, apoptosis and cancer signaling pathways." (PMID 33424592, 2020).
cancer (continued). "However, in the aggressive AR-negative CRPC cells, upregulation of VEGFA could drive expression of Slug through the VEGFA/VEGFR2 autocrine signaling axis in an AR-independent manner, which promotes cancer cell survival and positively influence PCa progression." (PMID 32198489, 2020). "We focused on biomarkers that exhibit the various hallmarks of cancer, and for which NIRF probes are already clinically available: epidermal growth factor receptor (EGFR), vascular endothelial growth factor-A (VEGF-A), integrin αvβ6 and epithelial cell adhesion molecule (EpCAM)." (PMID 32545676, 2020). "Nevertheless, our results indicated that neuropilin mediates cancer cell growth may rely on pathways independent of VEGFA." (PMID 31552163, 2019). "Furthermore, researchers hypothesized that fibroblasts may be activated by vascular endothelial growth factor A (VEGFA) signaling, thus inducing cancer development." (PMID 31906017, 2019). "We show that the absence of VEGFA/VEGR2 activation could presumably contribute to the control of extra-thoracic spreading of cancer cells in the virally induced cancer in sheep and in lepidic adenocarcinomas in humans." (PMID 29137669, 2017). "In human cancers, VEGFA expression was not altered but VEGFR2 was not expressed." (PMID 29137669, 2017). "The first antiangiogenesis drug bevacizumab (a monoclonal antibody for VEGFA) was launched in 2004 and many small molecules that inhibit the activity and signaling cascade of VEGF receptors (VEGFRs) have been developed and approved by the US FDA for the treatment of various types of cancer." (PMID 27657036, 2016). "Identified discriminatory cancer markers include matrix metalloproteinases (i.e., MMP1, MMP3, MMP9), cytokines (i.e., interleukin-6, interleukin-8, vascular endothelial growth factor A (VEGF-A), tumor necrosis factor α (TNF-α), transferrins, and fibroblast growth factors." (PMID 27999326, 2016). "In our present study, we further found that XBP1 regulate VEGF expression in cardiomyocytes, which is in a line with that XBP1 s can bind to two regions on the VEGFA promoter contributes to VEGFA expression in response to ER stress in human cancer cells and mouse embryonic fibroblasts." (PMID 26572862, 2015). "Importantly, we found that miR-361-5p levels are inversely correlated with VEGFA expression in SCC and in healthy skin, indicating that miR-361-5p could play a role in cancers." (PMID 23166713, 2012). "In addition to the inflammation pathway, several cancer-related pathways were identified from the global NSAIDs-regulating miRNA-gene subnetwork, including cell cycle (CDK6, CCND1, CCKN1A, and E2F1), proliferation (MYC), apoptosis (BCL2) and angiogenesis (VEGFA)." (PMID 27329603, 2016). "However, the regulation of angiogenesis-related cytokines in cancer cell is a very complicated network, we did not exclude other signal pathways which may modulate VEGFA expression and can be affected by miR-26a." (PMID 24194905, 2013). "However, the observed slight effects are likely not correlated with its targeting of VEGFA and may be the result of targeting other cancer related genes." (PMID 23166713, 2012). "After adjustments, the controls and cancer-affected tissue samples showed significantly higher HIF1A expression and slightly, but not significantly, higher VEGFA expression levels." (PMID 39888575, 2026). "In the metastatic site, the PV macrophage subset, which expresses CCR2 and VEGFA (but not TIE2), promotes cancer cell seeding through direct interactions with cancer cells at the vessel wall and subsequently promotes colonization." (PMID 39516356, 2024). "For example, genes such as VEGFA and EZR were significantly expressed in EC-1-Cancer cells, but genes such as PDE4D and AFDN were not expressed." (PMID 37124501, 2023). "Here, we have assessed the mRNAs of 61 diverse oncogenes and found half of them, including VEGFA and SNAIL1/2, are abundant in cancer EVs while absent in non-tumorigenic cell-derived EVs." (PMID 33921957, 2021).
cancer (continued). "Although VEGFA‒VEGFR2 inhibitors reduce the levels of VEGFA and VEGFR2 in the kidneys of patients with cancer, not all patients develop proteinuria." (PMID 33921219, 2021). "Positive correlation with cancer-promoting genes BCL2, BCLxL, HIF1A, VEGFA, ACTA2, CCL2, PTGS2, and CDKN1A, but not Ki67, was demonstrated, particularly for ILs’ receptors." (PMID 32512917, 2020). "In contrast, among potential target genes of miR-34a, miR-424, and miR-503, vascular endothelial growth factor A (VEGFA) and FOS-like 1 (FOSL1) expression did not exhibit clear correlations with poor prognosis in patients with basal-like cancer." (PMID 29872500, 2018). "We observed the overexpression of isoforms of genes C3orf17, FRMD4A, FZD6, HNRNPA2B1, POSTN, PRKAA1, RRBP1 and VEGFA, and the under expression of TRIP12 isoform (ENST00000428959) in ACC patients who are not free of cancer, which is a surrogate for poor ACC outcomes." (PMID 33035235, 2020). "Importantly, VEGFA and VEGFR2 proteins were not expressed in JSRV-induced cancers." (PMID 29137669, 2017).
infection (388 papers, 2005 to 2026). The state of being infected such as from the introduction of a foreign agent such as serum, vaccine, antigenic substance or organism. "By using ELISA, we found that the infection-caused upregulation of VEGFA, PDGFB, and ANGPTL4 in the brains of Egr-1−/− mice significantly decreased compared with that in WT mice." (PMID 38233877, 2024). "Among the five growth factors included in the assay, infection with the Omicron variant moderately upregulated the expression of vascular endothelial growth factor-A (VEGF-A) and platelet-derived growth factor-AA (PDGF-AA)." (PMID 38568894, 2024). "We also found that intervention of HIF-1α and VEGFA signaling affected infection outcomes caused by respiratory bacteria in mouse models." (PMID 36916939, 2023). "All of these findings suggest that HIF-1α and/or VEGFA represents a potential target to reduce the severity of infections caused by P. multocida." (PMID 36916939, 2023). "We further confirmed that intervention of HIF-1α–VEGFA signaling could mitigate infections caused by respiratory bacteria in mouse models, thereby presenting this pathway as a suitable candidate for therapy against respiratory bacterial infections." (PMID 36916939, 2023). "These macrophages were notably elevated in patients hospitalized more than 10 days after infection onset, and their presence correlated with increased expression of angiogenic and hypoxia-related genes such as VEGFA, FGF2, and HIF1." (PMID 41472298, 2025). "Pre-incubation with either HCMV variant for 24 h or 72 h before infection with A. fumigatus significantly and time-dependently suppressed gene expression and secretion of key cytokines such as CXCL8, VEGFA, IL-1α, IL-1β, IFN-γ, and TNF-α." (PMID 40980889, 2025). "Treatment with a VEGFA-blocking antibody attenuates vascular permeability and offers protection against P. multocida in mouse infection models." (PMID 36916939, 2023). "For example, infection by latent CMV has been shown to promote neovascularization in VEGFA-overexpressed mice." (PMID 36738354, 2023). "Ectopic LBH, αB-crystallin (CRYAB) and VEGFA expression was induced by lentiviral infection or plasmid transfection to explore their functions in modulating EMT and angiogenesis in NPC." (PMID 34975330, 2022). "This study indicated that CSFV Shimen infection triggered VEGFA responses in macrophages at both the transcription and translation levels." (PMID 30849965, 2019). "This process required the PCN033 infection-induced upregulation of VEGFA and Snail-1, which involves the activation of TLR2-MAPK-ERK1/2 signaling cascade." (PMID 27588479, 2016). "Meanwhile, the infection-induced generation of proinflammatory cytokines and chemokines promote the increase of VEGFA and Snail-1, thus also aggravating the damage of the TJ proteins." (PMID 27588479, 2016). "Notably, direct infection of HMVEC-Ls induced the upregulation of VEGFA, ANGPT1 (angiopoietin-1), and FGF2 gene expression, as well as upregulation of VEGF receptor genes FLT1, KDR, and NRP1." (PMID 37773065, 2023). "Our results demonstrated that P. multocida isolates of both human and animal origins could increase the permeability of respiratory epithelial barriers during infection, and this process was associated with the activation of the HIF-1α–VEGFA pathway." (PMID 36916939, 2023). "Moreover, production of proinflammatory cytokines and chemokines in response to infection also promoted the upregulation of VEGFA and Snail-1, therefore further mediating the BBB disruption." (PMID 27588479, 2016). "In vivo tests in mouse infection models demonstrated that P. multocida infection significantly increased epithelial permeability and increased the expression of vascular endothelial growth factor A (VEGFA) and endothelial nitric oxide synthase (eNOS) in murine tracheae and lungs." (PMID 36916939, 2023).
infection (continued). "Here, we found that mRNA level of VEGFA of wound tissues of AG‐, PRF‐, and PRP‐treated groups was significantly increased at day 12 post‐burn injury and infection." (PMID 39829200, 2025). "ANDV infection showed upregulation of cell type-specific viral entry genes (Calu-3: CD55 and ITGB3; hPSC-astrocytes: MERTK and VEGFA)." (PMID 40857262, 2025). "The engineered cell line producing engineered exosome was developed by infection with lentivirus containing three cargo genes (WNT10B, FGF7, and VEGFA) in HEK-293 cells." (PMID 40521098, 2025). "The Egr-1−/− mice were used to evaluate the contribution of Egr-1 to VEGFA, PDGFB, and ANGPTL4 production in response to the infection." (PMID 38233877, 2024). "At this time, the parasite was less able to invade new host tissues, resulting in reduced VEGFA and VEGFR2 expression and helping control the infection." (PMID 37936208, 2023). "Infections with P. multocida isolates from multiple hosts alter barrier functions and activate the HIF-1α–VEGFA pathway in human respiratory epithelial cells." (PMID 36916939, 2023). "Using BEAS-2B cells as a model, we demonstrated that infections by P. multocida isolates from different animals could induce an increase in respiratory epithelial permeability, and this process was also associated with the bacterial activation of HIF-1α–VEGFA signaling." (PMID 36916939, 2023). "Infection significantly increased the expression of ACE2, TMPRSS2, ADAM17, TGFB1, CTGF, VEGFA and FN1 but resulted in trends towards decreases in TIMP3 (p = 0.083) and AGF (p = 0.086) in A549 cells compared to control cells." (PMID 32664949, 2020). "Quantitative polymerase chain reaction and western blot analysis confirmed that VEGFA and PLAU were significantly up-regulated at both the transcription and translation levels after infection." (PMID 30849965, 2019). "Based on our results, we propose that coordinated expression of VEGFA and PLAU plays an important role in the inflammatory response of macrophages to CSFV Shimen infection." (PMID 30849965, 2019). "Western blot analysis confirmed the increased expression of VEGFA and uPA in macrophages after CSFV Shimen infection." (PMID 30849965, 2019). "In conclusion, we showed that VEGFA and PLAU were significantly up-regulated after CSFV Shimen infection." (PMID 30849965, 2019). "In contrast, we observed a much lower induction of VEGFA mRNA as well as the protein, in hBMEC upon HB101 infection, compared to that of PCN033 infection." (PMID 27588479, 2016). "VEGFA and ELR + chemokines appear to be induced by TNF and play a role in infection dissemination." (PMID 38036985, 2023). "Notably, Xpro-1595 therapy effectively regulated the expression of VEGFA and ELR + chemokines, which emerged as key factors contributing to infection dissemination." (PMID 38036985, 2023). "TNF-α, IL-1β, VEGFA, and ICAM-1 mRNA levels in tissues were detected, which were observed to be remarkably upregulated in the DR and DR + Lv-sh-NC groups whereas partially downregulated after Lv-sh-Cx43 infection." (PMID 36120455, 2022). "Furthermore, genes encoding pro‐inflammatory cytokines were upregulated on day 7 after infection, including TNF (TNF30), IL‐6 (IL‐631, 32) and VEGFA (VEGF‐A33) which have known functions in B‐T cell interactions or germinal centre development." (PMID 34169553, 2022). "VEGFA and uPA expression in macrophages was induced in a time-dependent manner upon treatment with CSFV Shimen, which was concurrent with the increased expression of E2 48 h after CSFV Shimen infection." (PMID 30849965, 2019). "Our findings suggest that co-expression of VEGFA and PLAU in macrophages contributes to CSFV Shimen infection and serves as a significant avenue for the strain to form an inflammatory microenvironment, providing new insight into the mechanisms of CSF caused by a virulent strain." (PMID 30849965, 2019).
infection (continued). "Temporal co-localisation of E2 and VEGFA was observed in the CSFV Shimen-infected cells, and the abundance of VEGFA in macrophages was significantly enhanced during the course of CSFV Shimen infection compared to that in uninfected controls." (PMID 30849965, 2019). "As we have demonstrated the involvement of MAPK-ERK1/2 signaling in meningitic E. coli induced upregulation of VEGFA and Snail-1, whether the TLR triggers this signaling event in response to infection was analyzed." (PMID 27588479, 2016). "Moreover, meningitic E. coli-induced high level of cytokines and chemokines are also important contributors in the infection-induced disruption of the BBB, via directly upregulating the VEGFA and Snail-1 in BMECs." (PMID 27588479, 2016). "The ChIP-seq data revealed the significant Egr-1-binding peaks in the promoter region of VEGFA (chromosome 6 position 43,771,366 − 43,771,763), PDGFB (chromosome 22 position 39,243,987 − 39,244,220), and ANGPTL4 (chromosome 19 position 8,363,766-8,364,203) in the infection group." (PMID 38233877, 2024). "Similarly, the blocking of VEGFA pathway could not prevent the significant upregulation of Snail-1 by infection." (PMID 27588479, 2016). "Since sVEGFR1 is minimally expressed in non-infected cells and an important negative modulator of angiogenesis by sequestering VEGFA and VEGFR2 activation in the circulatory system, we investigated the secretion of sVEGFR1 during SFTSV infection." (PMID 40789964, 2025). "Notably, HIF-1α is important for neutrophil survival in normoxia as well as hypoxia, and VEGFA and many other HIF-1α target genes, but not HIF1A itself, are upregulated following LVS infection including HK2, LDHA, PDK1 and SCL2A1." (PMID 35873156, 2022).